PDCD1LG2 (programmed cell death 1 ligand 2)
Diseases named in the same sentence as PDCD1LG2 in open-access papers (continued):
Sharing a sentence is not in itself a finding about the gene and the disease.
cancer (560 papers, 2008 to 2026). A tumor composed of atypical neoplastic, often pleomorphic cells that invade other tissues. "To determine the biological processes associated with pdcd1lg2 expression in cancers, we performed GSEA across 33 types of common human cancers in TCGA database." (PMID 37006239, 2023). "We performed a pan-cancer analysis using TIMER 2.0 and found that pdcd1lg2 expression was significantly positively associated with multiple infiltrating immune cells in various cancers, especially macrophages in COAD." (PMID 37006239, 2023). "The ROC curve was used to evaluate the diagnostic value of CD274 and PDCD1LG2 in pan-cancer analysis." (PMID 36276934, 2022). "CD27 and PDCD1LG2 (PDL2) showed significant association with cancer invasion signature in TCGA dataset." (PMID 35874720, 2022). "Analysis of data from The Cancer Genome Atlas (TCGA) identified that high PDCD1LG2 expression was associated with reduced overall and cancer-specific survival in patients with PDAC." (PMID 36138073, 2022). "In the current study, we assessed the expression of CD274 and PDCD1LG2 and analyzed their associations with clinical characteristics across 33 cancer types." (PMID 36276934, 2022). "Taken together, our findings provide clues for the association between CD274/PDCD1LG2 and cancer immunity, which require further experiment investigations to clarify." (PMID 33833994, 2021). "It appears that miR-93 is able to affect a number of factors such as programmed cell death 1 ligand 2 (PDCD1LG2) associated with cancer immunotherapy, G-protein coupled receptor 137C (GPR137C) and mitogen-activated protein kinase 2 (MAPK2)." (PMID 32612456, 2020). "Ligands for PD1 (CD274 encoding PD-L1 and PDCD1LG2 encoding PD-L2) were minimally expressed in cancer cells." (PMID 31427603, 2019). "LAMP3+ cDCs were characterized by high immune regulatory gene expression, including CD274 (encoding PD-L1) and PDCD1LG2 (encoding PD-L2), consistent with “mregDCs,” a subset of DCs co-expressing maturation and immunoregulatory genes identified in various cancers." (PMID 38012392, 2024). "Moreover, diagnostic values of CD274 and PDCD1LG2 in various cancers were confirmed using ROC curves." (PMID 36276934, 2022). "More importantly, the CD274/PDCD1LG2 expression was associated with the cancer immunity." (PMID 33833994, 2021). "Consequently, it is of great significance to comprehensively investigate the association of the CD274/PDCD1LG2 expression with TMB levels among the patients with cancer, using the TCGA-derived high-quality matched data." (PMID 33833994, 2021). "Notably, the abundance of macrophages was the most positively associated with pdcd1lg2 expression in multiple types of cancer, especially in COAD (Rho=0.917 for macrophage EPIC; Rho=0.496 for macrophage TIMER; Rho=0.818 for macrophage XCELL; Rho=0.913 for macrophage/monocyte MCP-COUNTER)." (PMID 37006239, 2023). "Then, immune checkpoints analysis shown that UBE2C had a negative correlation with immune checkpoints, such as CD274(PD-1), PDCD1(PD-L1), CTLA4, TIGIT, LAG3, HAVCR2, and PDCD1LG2 in a great many cancers." (PMID 38370368, 2024). "The expression of CD274/PDCD1LG2 is pivotal in immune cell infiltration in the TME across various cancers." (PMID 38833018, 2024). "Recently, an unbiased proteomics analysis has identified a significant up‐regulation of the immune checkpoint inhibitor, programmed cell death 1 ligand 2 (PD‐L2), in various chemotherapy‐induced senescent cancer cells." (PMID 39270064, 2024). "We discovered, through an unbiased proteomics screen, that the immune checkpoint inhibitor programmed cell death 1 ligand 2 (PD-L2) is highly upregulated upon induction of senescence in different types of cancer cells." (PMID 38267628, 2024). "The expressions of nearly all kinds of immune-related genes were significantly related to the expression of pdcd1lg2 in pan-cancer." (PMID 37006239, 2023).
cancer (continued). "First, the results of GSEA demonstrated that pdcd1lg2 played an important role in cancer immune response." (PMID 37006239, 2023). "The results showed that pdcd1lg2 expression was significantly and positively correlated with immune contexture and stromal contexture in almost all cancer types." (PMID 37006239, 2023). "PDCD1LG2 (PD-L2) has been reported to enhance the ability of immune invasion and was expected to be a potential cancer therapeutic target." (PMID 36676763, 2023). "We next examined the associations of TLR4 expression with 8 immune checkpoints (PD-L1, CTLA4, HAVCR2, LAG3, PDCD1, PDCD1LG2, SIGLEC15, and TIGIT), and TLR4 expression was widely associated with the 8 immune checkpoints in most cancer types." (PMID 37576399, 2023). "The most promising immune checkpoint therapeutic targets, CD274 (PD‐L1) and PDCD1LG2 (PD‐L2), were expressed at low levels in each cancer cell population." (PMID 36529697, 2023). "Last, pdcd1lg2 expression was significantly positively correlated to the immune score and stromal score in almost all kinds of cancers when analyzed using the ESTIMATE algorithm." (PMID 37006239, 2023). "All 33 types of common human cancer types in TCGA database and 12 types of human cancer queues in ICGC database expressed pdcd1lg2, though it exhibited inconsistent mRNA expression." (PMID 37006239, 2023). "Then, we performed a pan-cancer analysis of relationships between pdcd1lg2 expression and immune cell infiltration levels using TIMER 2.0." (PMID 37006239, 2023). "Although a variety of previous studies have demonstrated the expression and functions of CD274 and PDCD1LG2 in certain cancer types, these studies tended to focus on individual cancer types, which restricted the co-analysis of CD274 and PDCD1LG2." (PMID 36276934, 2022). "Materials and Methods: Differences in expression levels of CD274 and PDCD1LG2 were analyzed in diverse cancer types using The Cancer Genome Atlas (TCGA) and Genotype-Tissue Expression (GTEx) databases." (PMID 36276934, 2022). "The current findings showed that the expressions of multiple immune-related genes, including CXCL9, CXCL10, GZMB, and PDCD1LG2, were upregulated in cancer with high TME scores." (PMID 35242245, 2022). "In summary, our integrated analysis suggests that CD274 and PDCD1LG2 are suitable biomarkers for pan-cancer diagnostics." (PMID 36276934, 2022). "The TCGA and GTEx databases declared variable CD274 and PDCD1LG2 expression levels across 33 cancer types." (PMID 36276934, 2022). "Owing to their immunosuppressive function, CD274 and PDCD1LG2 levels were found to be positively correlated with most immunosuppressive molecules across cancers, and both had a significant correlation with TGCT." (PMID 36276934, 2022). "Programmed death 1 (PD-1) and its ligands, programmed death ligand 1 (PD-L1, or CD274) and PD-L2 (PDCD1LG2), are known as an immune checkpoint axis available to the cancer cells escaping from the immune destruction of T cells." (PMID 33833994, 2021). "Collectively, our comprehensive pan-cancer analysis has characterized CD274/PDCD1LG2 in different cancer cell lines and tissues of seven gastrointestinal cancer types." (PMID 33833994, 2021). "Using CCLE and TCGA databases, a large number of diverse types of cancers are obtained, which contributes to discovering the abnormal CD274/PDCD1LG2 expression among the different types of cancers." (PMID 33833994, 2021). "According to the results of CCLE analysis, CD274 and PDCD1LG2 showed inconsistent gene expression levels among the diverse cancer cell lines (p = 6.1e-20 and 6.9e-20), where pancreas cells had a relatively higher gene expression." (PMID 33833994, 2021). "According to this study, the CD274/PDCD1LG2 level was related to the immune infiltration levels in cancers." (PMID 33833994, 2021). "PDCD1LG2 (PD-L2)-specific T (CD4 or CD8) cells support anti-cancer immunity directly by killing their target cells." (PMID 33987093, 2021).
cancer (continued). "CD274 and PDCD1LG2 displayed inconsistent gene expression levels among the diverse cancer cell lines." (PMID 33833994, 2021). "TIGIT expression mediated infiltrated immune cells and positively correlated with the expression of LAG3, CTLA4, PDCD1 (PD-1), CD274 (PD-L1), PDCD1LG2 (PD-L2) in most of the cancer types." (PMID 34795387, 2021). "The results suggested that UBE2C expression was positively associated with the immune checkpoint-related genes in 31 cancers, which mainly included CD274, CTLA4, HAVCR2, LAG3, PDCD1, PDCD1LG2, SIGLEC15, and TIGIT." (PMID 34858987, 2021). "An analysis between CD274/PDCD1LG2 and a methylase inhibitor is expected to inject a new vitality into the cancer treatment." (PMID 33833994, 2021). "It was found that most cancer types showed a CD274/PDCD1LG2 alteration frequency, and the abnormal expression served as a prognostic factor in some cancer types." (PMID 33833994, 2021). "PANX1 was shown to be positively associated with some immune inhibitors such as CD274, PDCD1LG2, and TGFBR1 in a variety of cancers." (PMID 34796785, 2021). "A pan-cancer analysis of CD274/PDCD1LG2 is valuable for identifying a differential expression and its role in many cancer types." (PMID 33833994, 2021). "Programmed Cell Death 1 Ligand 2 (PD-L2), which is expressed on the surface of cancer cells, has recently attracted attention." (PMID 31623180, 2019). "EBV positive carcinomas show recurrent PIK3CA mutations, extreme DNA hypermethylation, and amplification of JAK2, CD274, and PDCD1LG2." (PMID 25859432, 2015). "Moreover, we found that KIF18A had a positive correlation with immune checkpoints, such as PD-1, PD-L1, CTLA4, TIGIT, LAG3, HAVCR2, and PDCD1LG2 in a great many cancers." (PMID 36830695, 2023). "The results of the association between IFN-γ score and ICG indicated that the IFN-γ scores of virtually all of the different cancers that were investigated had a positive association with the expression of TIGIT, IDO1, ICOS, CD86, CTLA4, HAVCR2, PDCD1LG2, and CD48." (PMID 37646041, 2023). "Herein, we screened the co-expression level of CD274/PDCD1LG2 using TCGA and Genotype-Tissue Expression (GTEx) databases and found that these expression levels were related to treatment outcomes in patients with cancer." (PMID 36276934, 2022). "Overall, these data indicated that CD274 and PDCD1LG2 could be established as biomarkers of therapeutic value in various cancers." (PMID 36276934, 2022). "Interestingly, the expression levels of CD274 and PDCD1LG2 differed quite much among these cancer types, identified by TCGA databases." (PMID 36276934, 2022). "Interestingly, we observed that CD274 and PDCD1LG2 expression levels were correlated with contradictory prognoses in different cancers." (PMID 36276934, 2022). "The CD274/PDCD1LG2 expression among the different cancer cell lines was reported." (PMID 33833994, 2021). "We further explored the correlation between YTHDC2 and eight immune checkpoint‐related genes and found that YTHDC2 was significantly associated with the expression of SIGLEC15, IDO1, CD274, HAVCR2, PDCD1, CTLA4, LAG3 or PDCD1LG2 in almost all types of cancers except for CESC and TGCT." (PMID 34312987, 2021). "Many types of gastrointestinal cancer have shown promising outcomes after checkpoint blockade immunotherapy; however, it remains largely unclear about the expression profiles of programmed death 1 (PD-1) ligands (CD274 and PDCD1LG2) in the context of human pan-cancer." (PMID 33833994, 2021). "Similarly, PD-L2 (PDCD1LG2: programmed cell death 1 ligand 2) is an immune checkpoint that contributes to immunosuppressive microenvironment for cancer; its expression is reversely correlated with RKIP expression in PC (Spearman r = −0.384, p < 2.2 × 10−16)." (PMID 34945007, 2021).
cancer (continued). "In various cancer types, programmed cell death-ligand 1 (PD-L1; encoded by the CD274 gene) and programmed cell death 1 ligand 2 (PD-L2, CD273, encoded by the PDCD1LG2) suppressed T cell activation and facilitated immune evasion by binding to PD-1 on lymphocytes." (PMID 34796785, 2021). "Notably, the present work also demonstrated that the expression of CD274/PDCD1LG2 was related to cancer immunity." (PMID 33833994, 2021). "By correlating drug sensitivity with the gene expression of cancer cell lines (n = 670), we identified Dasatinib, a potent Abl/Src inhibitor, with the efficacy negatively correlated with several immune biomarkers (CD274, CD47, PDCD1LG2), that are preferentially expressed by cancer cells." (PMID 32824422, 2020). "Also of notice, a pronounced number of critical immunomodulators, which were described in an immunogenomic analysis of major TCGA cancer data sets and included PDCD1LG2, BTN3A2, GZMA, BTLA, CD28, ICOS, and IDO1, were contained in the 358 DEG set." (PMID 32603365, 2020). "The miR-93 targets programmed cell death 1 ligand 2 (PDCD1LG2, also known as PD-L2), which is related to cancer immunotherapy, and G-protein coupled receptor 137C (GPR137C), and mitogen-activated protein kinase kinase kinase 2 (MAP3K2, also known as MEKK2) in the RAS-MAPK signaling." (PMID 30615673, 2019). "Given the higher expression of PDCD1, CD274 and PDCD1LG2 in pre-RA and RA synovial biopsies, and the development of IA in cancer patients, we reasoned that PD-1 pathway may be down-modulated in RA patients." (PMID 29489833, 2018). "Notably, CD274/PD-L1, PDCD1LG2/PD-L2, PDCD1/PD1, cytotoxic T lymphocyte-associated antigen 4 (CTLA4), T cell membrane protein 3 (TIM3; also known as HAVCR2), and lymphocyte activation gene 3 (LAG3) were correlated to FAM72A across different cancers." (PMID 36613817, 2022). "However, integrated studies considering CD274 and PDCD1LG2 across cancers remain limited." (PMID 36276934, 2022). "Furthermore, the correlation of CD274/PDCD1LG2 with cancer immunity was also explored." (PMID 33833994, 2021). "However, a specific gene expression of CD274/PDCD1LG2 in gastrointestinal cancers at a pan-cancer level remains largely unknown." (PMID 33833994, 2021). "Our research shows that PIEZO1 expression is positively correlated with key immune checkpoints, including CD274 (PD-L1), CTLA4, LAG3, PDCD1 (PD-1), PDCD1LG2 (PD-L2), and TIGIT across various cancer types." (PMID 40977743, 2025). "TMED2 expression was positively connected with important immune checkpoint markers such as CD274, HAVCR2, PDCD1LG2, and SIGLEC15 in numerous cancer types." (PMID 40519935, 2025). "The correlation between SLC2A1 expression and eight immune checkpoints (CTLA4, PDCD1, TIGIT, LAG3, CD274, HAVCR2, PDCD1LG2, and SIGLEC15) was further investigated across multiple cancer types." (PMID 40824962, 2025). "We examined the relationship between EIF5A2 and immune checkpoints using Spearman analysis and found that EIF5A2 was correlated with CD274, PDCD1LG2, and HAVCR2 in the majority of cancers and PDCD1, CTLA4, LAG3, SIGLEC15, and TIGIT in some tumors." (PMID 40964657, 2025). "In particular, Hypo-MS4 activity was positively associated with the expression levels of immune checkpoint genes, namely, CD274, PDCD1LG2, and IDO1, in multiple cancer types (P ≤ 0.01)." (PMID 38566132, 2024). "Subsequently, we also explored the correlation between the expression levels of LRP6 and the expression levels of common immune checkpoints in 33 cancers, such as SIGLEC15, IDO1, CD274, HAVCR2, PDCD1, CTLA4, LAG3 and PDCD1LG2." (PMID 38226972, 2024). "Remarkably, five genes (PDCD1LG2, CD48, IDO1, LAIR1, and PDCD1) were found to be present in both the cancer-immunity cycle inhibitors and checkpoint genes categories." (PMID 38540734, 2024).
cancer (continued). "Our analysis indicated a positive correlation between B3GNT5 and immune activation markers, including CD276, PVR, NT5E, STING1, and TNF-SF18, as well as immunosuppressive genes TGF-ΒR1, IL-10PR, KDR, CD274, PDCD1LG2, IL-10, and IDO1 in the pan-cancer cohort." (PMID 39671359, 2024). "A highly positive correlation between CD274 (PD-L1-encoding gene) and pdcd1lg2 expression in almost all cancers was observed in our results, which might suggest that targeting PD-L1 will not show apparent benefits since PD-L2 is still functional and plays a redundant role." (PMID 37006239, 2023). "Since immune checkpoint inhibitors (ICIs) have been a prominent topic in cancer treatment, the expression of eight ICIs (LAG3, HAVCR2, CD27, TNFRSF14, CTLA4, TMIGD2, TIGIT, and PDCD1LG2) were analyzed between groups in the study." (PMID 37405988, 2023). "PD1-related checkpoints were highly related to pyroptosis activities in different cancer types, including Programmed Cell Death 1 (PD-1, PDCD1), Programmed Cell Death 1 Ligand 1 (PD-L1, CD274), and Programmed Cell Death 1 Ligand 2 (PDCD1LG2)." (PMID 37863886, 2023). "We analyzed the expression profile of COMMD2 gene and ICGs (CD274, CTLA4, HAVCR2, LAG3, PDCD1, PDCD1LG2, SIGLEC15, and TIGIT) at a pan‐cancer level." (PMID 36205192, 2023). "Subsequently, the correlation between key pan-carcinoma molecules (including CTLA4, PDCD1LG2, IDO1, and HAVCR2) and CD86 was calculated." (PMID 37064861, 2023). "Our findings brought to light that PTX3 had a close and positive association with most ICIs (CD274, CTLA4, HAVCR2, LAG3, PDCD1, PDCD1LG2, TIGIT, and SIGLEC15) in TCGA cancers, except TGCT." (PMID 36139597, 2022). "Afterward, we evaluated the link between DTYMK expression and key immune checkpoints (CD274, CTLA-4, HAVCR2, LAG3, PDCD1, PDCD1LG2, SIGLEC15, and TIGIT) expression levels in pan-cancer." (PMID 36094557, 2022). "Since TMB, MSI, DNMT and MMR expression were proved associated with the efficiency of checkpoint-blocked therapy across various cancer types, the relationships between CD274/PDCD1LG2 and these markers were examined." (PMID 36276934, 2022). "The key immune checkpoints (CD274, CTLA-4, HAVCR2, LAG3, PDCD1, PDCD1LG2, SIGLEC15, and TIGIT) also had a significant relationship with DTYMK expression in approximately 20 kinds of cancers, except in MESO, PCPG, and UCS." (PMID 36094557, 2022). "In most cancers, CD274 and PDCD1LG2 showed significantly positive relationship with memory-activated CD4+ T cells but a negative correlation with naive CD4+ T cells." (PMID 36276934, 2022). "Thus, the relationship between CD274/PDCD1LG2 and the degree of immune cell infiltration was explored, based on TIMER, the data showed that CD274/PDCD1LG2 levels were positively associated with macrophages, dendritic cells, neutrophils, and CD8+ T cells in most cancers." (PMID 36276934, 2022). "These responsive T cells positively correlate with PD-L1+PD-L2+ DCs, PDL1+ CCR2+, or MMP9+ macrophages or MHC I/II+ cancer cells, mainly through costimulatory CD28-CD80, ICOS-ICOSLG, coinhibitory PDCD1-CD274/PDCD1LG2, HAVCR2-LGALS9, and CLTA4-CD80/CD86." (PMID 35514975, 2022). "As CD274/PDCD1LG2 levels were found related with the clinical characteristics of LGG and SKCM, GO, KEGG analysis, and GSEA were performed for these two cancers." (PMID 36276934, 2022). "We found that the expression level of GRWD1 was positively correlated with the expression levels of immune checkpoint-related genes (CD274, CTLA4, HAVCR2, LAG3, PDCD1, PDCD1LG2, SIGLEC15, and TIGIT) in most types of cancer, especially in STAD." (PMID 34616846, 2021). "In terms of co-inhibitors, GMFG showed a positive relationship with PDCD1LG2 (PD-L2) and SLAMF7 in most cancers." (PMID 33863293, 2021). "Thirdly, we observed an increased expression of several immune checkpoints, including PD-L1 (CD274), PD-L2 (PDCD1LG2), CD73 (NT5E), and galectin-3 (LGALS3) in the nutlin-3 resistant cancer cells." (PMID 35582010, 2021).